LYVE1 (lymphatic vessel endothelial hyaluronan receptor 1)
Diseases named in the same sentence as LYVE1 in open-access papers (continued):
Sharing a sentence is not in itself a finding about the gene and the disease.
thyroid cancer (1 paper, 2018). "Expression of the lymphatic endothelial cell marker LYVE-1 was also correlated with a high level of SRC-1 expression in thyroid cancer tissue." (PMID 29717026, 2018). "Furthermore, an immunohistochemistry analysis confirmed that the proteins SRC-1/VEGFC (positive: 13/20 and positive: 15/20) and SRC-1/LYVE-1 (positive: 13/20 and positive: 18/20) were highly expressed in a majority of thyroid cancer specimens." (PMID 29717026, 2018). "The levels of SRC-1 expression in samples of thyroid cancer tissue, and their correlation with VEGFC levels and LYVE-1-positive lymphatic vessels were analyzed." (PMID 29717026, 2018).
tongue squamous cell carcinoma (1 paper, 2024). A squamous cell carcinoma that arises from the tongue. "A notable correlation was found between low LYVE-1-positive vessel density in preinvasive and peritumoural submucosal regions in tongue squamous cell carcinomas (TSCC) and the occurrence of regional lymph node metastasis." (PMID 38791985, 2024). "In relation to tongue squamous cell carcinomas, a reduction in the density of LYVE-1-positive lymphatic vessels at the tumour invasion site and submucosal tissue around the tumour may serve as indicators of lymph nodes involvement." (PMID 38791985, 2024).
tuberculosis (1 paper, 2024). A chronic, recurrent infection caused by the bacterium Mycobacterium tuberculosis. "LYVE1 is a ligand-specific transporter trafficking between intracellular organelles and the plasma membrane, and was identified as a biomarker for diagnosis of tuberculosis." (PMID 39431015, 2024).
uveal tumor (1 paper, 2015). "Staining for LV endothelial hyaluronan receptor-1 (Lyve-1), a specific marker of LVs revealed extensive lymphangiogenesis in TDLNs from mice with large uveal tumor (>10 mm2)." (PMID 26575174, 2015).
tumor (289 papers, 2004 to 2025). "A subset of perivascular tumor-associated macrophages (PvTAMs), marked by the expression of the lymphatic vessel endothelial hyaluronan receptor-1 (LYVE-1), has previously been identified." (PMID 40768602, 2025). "We recently demonstrated that a subset of perivascular tumor-associated macrophages (PvTAMs) exclusively express HO-1 and coexpress lymphatic vessel endothelial hyaluronan receptor-1 (LYVE-1) in MMTV-PyMT tumors." (PMID 40627458, 2025). "The ECM remodeling phenotype of LYVE-1+ macrophages that we previously identified in the normal mammary gland was found to be conserved in tumor-associated macrophages as identified by scRNA-seq analysis." (PMID 38717149, 2024). "Serial sectioning and immunohistochemical staining for LYVE1 were performed to assess tumor‐associated lymphangiogenesis by measuring MLVD, and its relationship with SLC7A2 expression was examined." (PMID 39382373, 2024). "Similar to the 4T1 model, LYVE-1+ and F4/80+ macrophages were found to be associated with the tumor margin." (PMID 38717149, 2024). "Similar to human GPR182, the expression of mouse GPR182 on LYVE-1-positive LECs in normal skin is limited; however, it is strongly expressed in tumor-associated LECs, and LECs seemed to be the main source for GPR182 in tumors." (PMID 35013216, 2022). "The presence of Lyve-1+ macrophages has been documented in tumors, and these cells have been implicated in lymphatic vessel remodeling and tumor progression." (PMID 32479261, 2020). "Morphometric analyses indicate a significant increase in the relative area fraction occupied by LYVE1+ tumor-associated lymphatic vessels in diaphragm specimens removed from mice injected with BACH1-overexpressing ES2 cells." (PMID 32132179, 2020). "The hyaluronan receptor LYVE-1 has been widely used for the detection of tumor-associated lymphatic vessels in different types of tumors." (PMID 27505247, 2016). "While the contributions of HA interactions with LYVE-1 to macrophage functions are even less well understood, recent interest in LYVE-1 as a marker of tumor-associated macrophages suggests that further studies of these interactions are warranted." (PMID 26106384, 2015). "This research intended to study the surface content of HA on tumor cells and analyze cell adhesive changes caused by the interaction between HA and its lymphatic endothelial receptor (LYVE-1)." (PMID 23717428, 2013). "To analyze tumor-associated lymphatic vessels, we double-stained tumor sections with antibodies specific for mouse LYVE-1 and CD31 (Pecam)." (PMID 22797548, 2012). "Second, measurement of the LYVE-1-positive areas in tumor-associated LNs indicated extensive lymphangiogenesis." (PMID 23031500, 2012). "Immunohistochemical quantification of the LYVE-1-positive area revealed lymphangiogenesis in all tumor-associated LNs." (PMID 23031500, 2012). "Tie2 expressing monocytes (TEMs) have been reported to express F480+/CD11c−/Ly-6C−/LYVE-1+ and implicated in promotion of tumor angiogenesis." (PMID 22396739, 2012). "Another interesting line of research involves LYVE-1-positive tumor associated macrophages that have indeed been associated with tumor lymphangiogenesis." (PMID 18047671, 2007). "In addition, we show that LYVE-1+ macrophages are associated with HA-enriched regions at the tumor periphery, outside of the tumor parenchyma." (PMID 38717149, 2024). "Furthermore, LYVE1 reportedly controls migratory and metastatic phenotypes in cancers, which account for approximately 90% of tumor-associated deaths." (PMID 37810197, 2023). "Interestingly, the upregulation of miR-155 was associated with a decreased level of VEGF-C and LYVE-1, two important markers for LECs and tumor-associated lymphangiogenesis." (PMID 33172072, 2020).
tumor (continued). "Further, other studies have shown that down regulation of tumour suppressive miR-126 and miR-128 results in the promotion of tumour-associated lymphangiogenesis, which was assessed by the subsequent reduction of a lymphangiogenic marker LYVE1." (PMID 31277414, 2019). "CD31, D2-40, and LYVE-1 were found to be positive in tumor-associated macrophages." (PMID 30781402, 2019). "However, LYVE-1 has also been found to be expressed by other cell types, such as Kupffer cells and tumor-associated macrophages (TAMs)." (PMID 29262593, 2017). "Lyve-1 deficiency led to a significantly increased tumor end weight." (PMID 29262593, 2017). "The lymphatic endothelial receptor LYVE-1 has been implicated in both uptake of hyaluronan (HA) from tissue matrix and in facilitating transit of leukocytes and tumor cells through lymphatic vessels based largely on in vitro studies with recombinant receptor in transfected fibroblasts." (PMID 26823460, 2016). "Tumours derived from ezrin-deficient cells demonstrated a significant reduction in lymphangiogenesis compared to MDASrc cells, as indicated by lymphatic vessel markers lyve-1 and podoplanin (respectively)." (PMID 25231728, 2014). "Some CCL21 staining showed spotty co-localization with LYVE-1 along the walls of lymphatic vessels in the lymph nodes, although most immunolocalization of the chemokine ligand was associated with metastatic tumor cells." (PMID 21172016, 2010). "Regional lymph nodes were characterized by lymphatic proliferation in tumor-bearing mice (with a mean 2.85 - fold increase in the total lymph node lymphatic conduit, as measured by LYVE-1 immunoreactivity, in tumor-associated lymph nodes as compared to non-tumor associated nodes; P = 0.004)." (PMID 21172016, 2010). "Also here, GFP+ cells were found integrated into tumor-associated lymphatic endothelium, detected by LYVE-1 or Podoplanin expression." (PMID 19759906, 2009). "Thus, further studies were performed to determine whether tumor-associated LYVE-1+ macrophages modulate HA in the tumor microenvironment." (PMID 38717149, 2024). "Spatial RNA profiling from 4 KS samples from patients with KS+KAD identified increased abundance of lymphatic endothelial cells, elevated LYVE1 expression in LANA-1+ tumor areas as compared to LANA- areas." (PMID 41409683, 2025). "Normal mammary fat pads (MFPs) and tumor sections (n = 5 per group) were double-stained for Lyve-1 to identify single M-LECP cells and eight proteins known to promote cell fusion including CD36, CD98, CD209, Dap12, Dc-stamp, Sirp-a, Sirp-b1, and stabilin-1." (PMID 40507286, 2025). "Macrophages_LYVE1 also expressed high levels of LYVE1, RNASE1, STAB1, CD163, and MARCO, which are associated with macrophage function and tumour immunosuppression." (PMID 40759637, 2025). "Normal and contralateral MFPs in tumor-bearing mice contained significantly lower levels of BM-derived Lyve-1+ cells (~20%) and hybrid lymphatic vessels (2–3%) compared with tumor counterparts (p-values < 0.01)." (PMID 40507286, 2025). "Blocking HA/LYVE-1 interactions with antibodies suppresses cell growth and movement, lowers lymphatic vessel numbers, decreases primary tumor size, and prevents lymph node metastasis in breast cancer models in mice." (PMID 40507943, 2025). "Staining of lymphatic vessel endothelial receptor-1 (LYVE-1) was performed in the subcutaneous tumor derived from LLC_NC and LLC_shFGL1." (PMID 41024301, 2025). "CD31(Pecam1) and LYVE1(Lyve1) expression in tumor tissues of the orthotopic HCC mouse models were also identified by IHC analysis, which was shown by the representative images." (PMID 40685403, 2025). "Compared with the peritumor area, CCL21, CCL19 and Pecam1 were more highly expressed in the tumor area, whereas Lyve1 had lower expression." (PMID 40685403, 2025). "This explains, for instance, why CSF-1 knockout mice and those treated with a CSF-1 inhibitor have significantly reduced densities of tumor Lyve-1+ cells and lymphatic vessels." (PMID 40507286, 2025).
tumor (continued). "It was shown that upon depletion of LYVE1+ macrophages, there was an excessive accumulation of HA, which had suppressive properties with respect to tumor cells." (PMID 39851489, 2025). "Collectively, these data show that the majority of M2-type TAMs in BC models including fusogenic Lyve-1+ myeloid cells are derived from the bone marrow and that a substantial portion of tumor lymphatic vessels undergo fusion." (PMID 40507286, 2025). "FOLR2+LYVE1+ Mo-Mp correlates with the remission of RA, which is in line with its known role in pro-tumor immunology via inducing immunosuppression." (PMID 38601143, 2024). "In this experiment, 86% to 94% of differentiated GFP+ cells were positive for Lyve-1, Ter-119 and CD3e immediately prior to transfer, but only 10% of tumor-residing GFP+ cells displayed this profile 4 weeks after transfer." (PMID 38640116, 2024). "In the cases of human IBC, similar membrane podoplanin, membrane LYVE1, and nuclear Prox1 immunoreactivities were observed surrounding the tumor emboli." (PMID 39669476, 2024). "The observations that the vast majority of tumor emboli in Mary-X fall within lymphatic channels were confirmed by companion podoplanin, LYVE1, and Prox1 immunocytochemical studies." (PMID 39669476, 2024). "Because of the observed reduction in tumor growth, further studies were performed to assess the effects of LYVE-1+ macrophage depletion on proliferation and apoptosis in the tumor." (PMID 38717149, 2024). "Although Lyve-1 TAM accounts for a small percentage of live cells within the tumor mass, their role is critical for tumor progression." (PMID 39086395, 2024). "Further studies are needed to assess expression levels of hyaluronidases and HA synthases in primary tumor-derived LYVE-1+ macrophages." (PMID 38717149, 2024). "CD206+ macrophages were found in both the tumor parenchyma and the peritumoral stroma, while LYVE-1+ macrophages were primarily localized in the tumor stroma." (PMID 38717149, 2024). "In further studies focused on investigating the functions of LYVE-1+ macrophages in the tumor microenvironment, we demonstrate that LYVE-1 expression correlates with an increased ability of macrophages to bind, internalize, and degrade hyaluronan." (PMID 38717149, 2024). "Immunohistochemical staining for the LV marker, LYVE-1, in tumor sections, showed that the density of LVs obviously decreased after anlotinib or SAR131675 treatment." (PMID 38616190, 2024). "Regarding the retention component of nanomedicine tumour targeting, we particularly looked at LYVE-1+ lymphatic vessels and F4/80+ TAM." (PMID 38589466, 2024). "On the basis of our findings that LYVE-1+ macrophages are associated with a phenotype linked with ECM remodeling, which is important for tumor growth and progression, we sought to examine the presence and function of LYVE-1+ macrophages in tumors." (PMID 38717149, 2024). "CAFs (α-SMA+) and lymphatic vessels (PDPN+ or LYVE1+) were abundant in CCA tumor tissues compared with those in normal liver tissues and para-tumoral tissues, and were spatially close to each other, suggesting an interaction between them." (PMID 37307823, 2024). "LYVE-1+ macrophage depletion led to a reduction in growth of tumor cells in the lung following tail vein injection, indicating that LYVE-1+ macrophages support lung colonization." (PMID 38717149, 2024). "The accumulation of HA observed in the context of LYVE-1+ macrophage depletion is consistent with a potential tumor suppressive role, possibly by acting as a barrier to tumor cell migration or enhancing sequestration of growth factors." (PMID 38717149, 2024). "Besides, IHC staining of lymphatic endothelial-specific antibody LYVE-1 suggested that tumor-associated lymphangiogenesis correlated with increased nodal spread and higher recurrence risk, suggesting that approaches targeting lymphangiogenesis could have therapeutic potency in ICC." (PMID 38926350, 2024).
tumor (continued). "Further studies were performed to evaluate the contributions of LYVE-1+ macrophages to tumor growth using the Lyve1CreCsf1rfl/fl and Csf1rfl/fl mice." (PMID 38717149, 2024). "Together, these findings indicate that LYVE-1+ macrophages represent a tumor-promoting anti-inflammatory subset of macrophages that contributes to hyaluronan remodeling in the tumor microenvironment." (PMID 38717149, 2024). "The currently available anti-LYVE-1 antibodies allow for in vivo fluorescence imaging of lymphatic vessels and the disseminating tumour cells, and are used for positron emission tomography (PET) scanning." (PMID 38791985, 2024). "In conjunction with the increased HA accumulation in the tumors from LYVE-1+ macrophage-depleted mice, these findings suggest that LYVE-1+ macrophages contribute to HA degradation in the tumor microenvironment." (PMID 38717149, 2024). "Mice treated with αCD20-EndoP125A demonstrated a significant reduction in the total amount of both CD34+ and LyVE-1+ tumor vessels compared to all other treatments." (PMID 39594584, 2024). "GFP+/Lyve-1+/CD11b+ macrophages were identified on tumor sections by triple staining and evaluated for co-expression of erythroid and T-cell lymphoid markers." (PMID 38640116, 2024). "The immunocompetent, syngeneic EMT6 tumor model replicated the progenitor behavior in a xenograft model: nearly 100% of EMT6-recruited Lyve-1+ cells expressed CD11b but only 1–3% co-expressed either Ter-119 or CD3e." (PMID 38640116, 2024). "While we cannot be certain that tumor-residing Lyve-1+ cells are derived directly from the BM generated Lyve-1+ cells, our adoptive transfer experiment is consistent with this interpretation." (PMID 38640116, 2024). "Given the extensive studies focused on LYVE‐1+ macrophages, targeting LYVE‐1 has been investigated in tumor models." (PMID 38426622, 2024). "FOLR2+LYVE1+ macrophages have pro‐tumor immunological functions in colorectal tumors and are related to unfavorable prognosis." (PMID 39494816, 2024). "There is now growing evidence to suggest this tumour cell HA coat can contribute to metastasis by facilitating lymphatic invasion of either individual tumour cells or tumour emboli via LYVE-1, perhaps in a similar manner to the trafficking of immune cells." (PMID 37606814, 2024). "Together, these findings suggest that in addition to ECM modulation, LYVE-1+ macrophages also serve an anti-inflammatory function within the tumor microenvironment." (PMID 38717149, 2024). "Consistent with the scRNA-seq results, FOLR2 expression was also positively correlated with TRM-related genes (CD163, MRC1, CD163L1 and LYVE1) in the whole-tumor transcriptome from the TCGA STAD database." (PMID 39702278, 2024). "No changes in LYVE-1+ macrophage frequency were found between tumor sizes; however, a reduction in LYVE-1+ macrophage count was found in the 1.5 cm3 tumors." (PMID 38717149, 2024). "LYVE-1 transports hyaluronic acid from tissues to the lymphatic system and regulates the migration of tumor cells in and out of lymphatic vessels, making it closely related to tumor lymphangiogenesis." (PMID 37286729, 2023). "Recent studies have found that LYVE-1 can bind to growth factors, such as VEGF-C, and participate in the autocrine and paracrine regulation of tumor-associated HLECs growth and migration." (PMID 37286729, 2023). "Additional macrophage-related markers i.e., Lyve-1 or S100A9 expressed inside the tumor chunks exhibiting loop-like patterns; F4/80+ staining appeared next to PAS+ VM tubes." (PMID 36781833, 2023). "The expression of HIF-1α, ALKBH5, and lymphatic density (LYVE-1 marker) was significantly elevated in tumor tissues." (PMID 36632222, 2023). "ENPP2 was 2.4-fold down-regulated in tumour tissue, and LYVE1 was 2.8-fold down-regulated in high-grade cancer compared to low-grade cancer." (PMID 37509322, 2023). "LYVE1 labelling also confirmed a denser lymphatic network in VEGF222/NF tumours compared with the control group (P < 0.05)." (PMID 36810959, 2023).